ENG (endoglin)
Diseases named in the same sentence as ENG in open-access papers (continued):
Sharing a sentence is not in itself a finding about the gene and the disease.
anemia (4 papers, 2021 to 2025). A reduction in the number of red blood cells, the amount of hemoglobin, and/or the volume of packed red blood cells. "Altogether, these data demonstrated that Endoglin-deficient zebrafish develop lethal congestive heart failure and anemia." (PMID 37264878, 2023). "Our results demonstrate that zebrafish Endoglin deficiency elicits a chronic hypoxic response, which results in increased erythropoiesis and hypochromic anemia in late stages." (PMID 37264878, 2023). "Using a CRISPR/Cas9 endoglin mutant, we demonstrate that homozygous mutants die from congestive cardiomyopathy, accompanied by iron-deficiency anemia, from 1 month postfertilization." (PMID 37264878, 2023). "The logistic regression analysis confirmed truncating variants as a significant predictor of anemia, along with sex and age, while ENG genotype alone was not an independent risk factor." (PMID 40648782, 2025).
Chronic colitis (4 papers, 2014 to 2019). A chronic inflammatory disease of the large intestine (colon, cecum and rectum). "This is also in agreement with the impaired resolution of inflammation reported in an endoglin heterozygous HHT1 mouse model of chronic colitis." (PMID 31242676, 2019). "For instance, Ardelean34 showed that a VEGF monoclonal antibody could ameliorate chronic colitis induced by DSS in Endoglin heterozygous mice." (PMID 30324649, 2018). "Thus, an inflammation model of dextran sodium sulfate (DSS)-induced chronic colitis revealed more leukocyte infiltration in the gut and a more severe colitis phenotype in endoglin heterozygous (Eng+/-) mice relative to control animals." (PMID 25709613, 2014).
chronic thromboembolic pulmonary hypertension (4 papers, 2016 to 2020). Chronic thromboembolic pulmonary hypertension (CTEPH) is characterized by the persistence of thromboemboli in the form of organized tissue obstructing the pulmonary arteries. "Increased levels of circulating endoglin+ endothelial MPs in the plasma of chronic thromboembolic pulmonary hypertension (CTEPH) patients improved the survival and proliferation of recipient cultured primary human pulmonary endothelial cells, thus demonstrating a therapeutic role of these particles." (PMID 32641036, 2020).
coronary artery disease (4 papers, 2009 to 2021). "Another previous study reported that plasma endoglin was a marker for predicting cardiovascular events in patients with coronary artery disease following percutaneous coronary intervention." (PMID 27306149, 2016). "Among hypoxia-responsive genes identified in our in vitro hypoxic system, we also found potential cardiac biomarkers (BIRC5, ENG, HMOX1, VEGF, STC1, STC2, and SERPINE1) which they may have potential clinical value in the diagnosis and prognosis of coronary artery diseases." (PMID 34685725, 2021).
endometrial cancer (4 papers, 2019 to 2025). Primary or metastatic malignant neoplasm involving the endometrium (mucous membrane that lines the endometrial cavity). "Endoglin’s assessment, together with microvessel density (MVD), suggests that it can be regarded as a promising diagnostic marker in women with endometrial cancer." (PMID 34501347, 2021). "According to the clinical studies, this step in TGFβ signaling is impaired since the expression of two TGFβ co-receptors, i.e., betaglycan and endoglin, is changed in endometrial cancer." (PMID 34501347, 2021). "In endometrial cancer, endoglin displays significant protein up-regulation, with concomitant not altered mRNA expression." (PMID 34501347, 2021). "The inclusion criteria of literature selected for this review included the search in PubMed of the National Library of Medicine using the following keywords: “TGFβ1-3” or “TGFβR1” or “TGFβR2” or “Smad1-7” or “betaglycan/TGFβR3” or “endoglin/CD105” and “human endometrium” or “endometrial cancer”." (PMID 34501347, 2021).
esophageal squamous cell carcinoma (4 papers, 2015 to 2024). Esophageal squamous cell carcinoma (ESCC) is a type of esophageal carcinoma (EC) that can affect any part of the esophagus, but is usually located in the upper or middle third. "For example, endoglin was reported to be critically downregulated in numerous esophageal squamous cell carcinoma tissues, due to promoter hypermethylation of the endoglin locus." (PMID 26228095, 2015). "Similar findings have been reported in esophageal squamous cell carcinoma, where a lack of endoglin expression was associated with decreased migration and colony formation in vitro." (PMID 32059544, 2020). "ENG is a candidate tumor-suppressor gene of esophageal squamous cell carcinoma." (PMID 28178989, 2017).
head and neck squamous cell carcinoma (4 papers, 2017 to 2026). A squamous cell carcinoma that arises from any of the following anatomic sites: lip and oral cavity, nasal cavity, paranasal sinuses, pharynx, larynx, and salivary glands. "There is also blood vessel enrichment of endoglin in ovarian tumors and head and neck squamous cell carcinoma." (PMID 41532547, 2026).
hemangioma (4 papers, 2015 to 2025). A benign vascular lesion characterized by the formation of capillary-sized or cavernous vascular channels. "- Meningiomas: WT1- Hemangiomas: VEGFR2, Endoglin (CD105)- Melanocytic nevi: MART-1, BRAF, NRAS mutations- Lipoma: HMGA2-expressing cells." (PMID 40630962, 2025). "Strong expression of Endoglin was detected in all 26 proliferating phase hemangioma specimens, and endoglin staining was decreased dramatically in the 10 involuting phase hemangioma specimens." (PMID 26308070, 2015). "Further, it was observed that in human hemangioma cells, endoglin could compete with the PP2A/A, C subunits for binding to the PP2A/B subunit, thereby resulting in dissociation of the B subunit from the PP2A complex." (PMID 26308070, 2015). "Moreover, endoglin, a molecule that is specific to newly formed endothelial cells, was found to cause dissociation of the B subunit from the PP2A AC core enzyme in primary human proliferating hemangioma endothelial cells." (PMID 26308070, 2015). "While, in the revoluting phase of hemangioma, the decreased level of endoglin abolishes its binding to PP2A, resulting in restoration of PP2A activity and the regression of hemangioma." (PMID 26308070, 2015).
intrauterine growth restriction (4 papers, 2011 to 2020). "Other biomarkers such as soluble endoglin (s–Eng), P–selectin, Cell free fetal DNA (cfDNA), placental protein 13 (PP–13) are being evaluated as predictors of pre–eclampsia and intrauterine growth restriction (IUGR)." (PMID 29163938, 2017). "In turn, Endoglin has been figured out as the causative factor for diseases associated with vascular dysfunction like hereditary hemorrhagic telangiectasia-1 (HHT-1), pre-eclampsia, and intrauterine growth restriction (IUPR)." (PMID 33287465, 2020).
liver cancer (4 papers, 2016 to 2025). An epithelial or non-epithelial malignant neoplasm that arises from the liver. "Additional relevant biomarkers such as Mesothelin, Endoglin, AFP, and CEA contribute to classification, with color-coded SHAP values showing their differential impact between Ovarian and Liver cancer." (PMID 40217526, 2025). "Endoglin (CD105) expression is increased in actively dividing endothelial cells, including those found in liver cancers." (PMID 37374319, 2023).
malaria (4 papers, 2010 to 2019). Malaria is a serious and sometimes fatal disease caused by a parasite that commonly infects a certain type of mosquito which feeds on humans. "We measured the soluble forms of ICAM-1 (sICAM-1) and the TGF-β receptor endoglin (s-endoglin), which have both been shown to be increased in severe malaria, and soluble FMS-like tyrosine kinase-1 (sFlt-1), which has been implicated in placental malaria." (PMID 21364762, 2011). "For example, an increase of the soluble Endoglin has been shown in severe malaria." (PMID 20540722, 2010). "s-endoglin was found to be increased in Gabonese children with severe malaria compared to UM, but we did not replicate these results." (PMID 21364762, 2011).
Obesity (4 papers, 2012 to 2025). Accumulation of substantial excess body fat. "Obesity was also associated with increased expressions of angiogenesis-related proteins, in particular, angiogenin, endoglin, endostatin, endothelin-1, IGFBP-3, leptin, MMP-3, PAI-1, TIMP-4, CXCL16, platelet factor 4, DPPIV and coagulation factor III." (PMID 22748184, 2012). "It has recently been shown that heterozygous endoglin deficiency in mice decreases insulin secretion in an animal model of obesity, highlighting a potential role for endoglin in the regulation of islet function." (PMID 27456002, 2016). "However, the effects of endoglin on adipose tissue remodeling in obesity are still elusive." (PMID 22748184, 2012). "Furthermore, the roles of ENG, FABP4, and CADM1 in critical biological processes such as vascular function, lipid metabolism, immunity, and adipose tissue regulation highlight the complex, and to some extent distinct etiology of childhood obesity from that of obesity presenting later in life." (PMID 41398348, 2025).
rectal cancer (4 papers, 2015 to 2024). A primary or metastatic malignant neoplasm that affects the rectum. "The aim of this study was to examine the expression of endoglin (CD105) in resected rectal cancer and to evaluate the relationship between microvessels density (MVD), clinicopathological factors, and survival rates." (PMID 26089870, 2015). "In this study, we aimed to analyze the gene and protein expression levels of two angiogenic markers, VEGF and soluble Endoglin, during different tumor stages as well as at different stages of cancer treatment, to predict the diagnosis and evolution of colon and rectal cancer." (PMID 32434528, 2020). "The role endoglin in the Dukes B rectal cancer is still unexplored." (PMID 27102733, 2016). "The aims of this study were to examine immunohistochemical expression of endoglin in resected rectal cancer and investigate the relationship of tumor recurrence and other clinicopathological variables to the endoglin-assessed microvessel density of the tumor tissue and distal resection margins." (PMID 27102733, 2016).
rhabdomyosarcoma (4 papers, 2018 to 2023). A rare aggressive malignant mesenchymal neoplasm arising from skeletal muscle. "We found a specific expression of endoglin (CD105) in endothelial cells of all the rhabdomyosarcoma specimens analyzed." (PMID 29304781, 2018). "Endoglin expression is also considered to be promising prognostic marker in rhabdomyosarcoma." (PMID 36844233, 2023). "In rhabdomyosarcoma, ENG expression was also exclusively detected in tumor vessels." (PMID 35955799, 2022). "It was shown that MVD calculated using endoglin staining was a reliable marker of more advanced disease, lymph node metastases and poor prognosis in HNSCC and in rhabdomyosarcoma." (PMID 36844233, 2023).
soft tissue sarcoma (4 papers, 2019 to 2024). A malignant neoplasm arising from muscle tissue, adipose tissue, blood vessels, fibrous tissue, or other supportive tissues excluding the bones. "A recent xenograft study showed that combination treatments with TRC105 and PD901 (anti-MEK) inhibited soft-tissue sarcomas and concluded ENG would be a promising therapeutic target." (PMID 38791148, 2024). "Hence, targeting endoglin was well-positioned for soft tissue sarcomas, where both the cancer cells and the supporting vessels would be vulnerable to endoglin inhibition." (PMID 33182685, 2020).
Ureteral obstruction (4 papers, 2014 to 2022). Obstruction of the flow of urine through the ureter. "For example, the model of tubulointerstitial fibrosis induced by unilateral ureteral obstruction (UUO) demonstrated an increase in endoglin mRNA and protein expression in the obstructed kidney." (PMID 34768419, 2021). "Renal expression of endoglin was upregulated in murine kidneys with tubulointerstitial fibrosis induced by unilateral ureteral obstruction (UUO) and renal irradiation, and such renal fibrosis was attenuated in endoglin heterozygous knockout mice." (PMID 29937525, 2018). "For this purpose, a transgenic mouse which ubiquitously overexpresses human L-Endoglin (L-ENG+) was generated and unilateral ureteral obstruction (UUO) was performed in L-ENG+ mice and their wild type (WT) littermates." (PMID 25313562, 2014).
cerebrovascular diseases (3 papers, 2017 to 2022). "The ENG/sENG axis is regulated in various cerebrovascular diseases." (PMID 35806090, 2022).
cholestasis (3 papers, 2013 to 2026). Impairment of the bile flow caused by obstruction within the liver, or outside the liver in the bile duct system. "Further, when clinical cholestasis markers were compared with the novel modalities for CFLD diagnosis assessed in this report, Bland-Altman Analyses revealed the presence of a proportional error in the agreement of γGT and the biomarkers TIMP-4 and Endoglin and in the agreement of ALP and TE." (PMID 23516586, 2013).
congenital heart disease (3 papers, 2014 to 2021). A heart disease that is present at birth. "For example, variants in the endoglin gene are linked with PAH associated with connective tissue disease, polymorphisms in estrogen-related genes may impact the risk of portopulmonary hypertension, and SOX17 have been implicated in PAH associated with congenital heart disease." (PMID 33996849, 2021). "Thus, ALK1 was upregulated in monocrotaline-induced PAH, TGF-β and ALK1 where increased in a lamb model of congenital heart disease, whereas ALK1 and ENG were downregulated in another study." (PMID 24956016, 2014).
dengue (3 papers, 2022 to 2025). "A recent study analyzing the expression of endoglin (EDG) and Syndecan-1 (SDC1) from activated endothelial cells during plasma leakage in critical phase of dengue showed significant correlation in predicting dengue severity." (PMID 35055629, 2022). "The authors observed a steady and significant increase in the levels of protein and mRNA of both the endoglin and syndecan-1 towards defervescence which is considered a critical phase in both severe and non-severe dengue cases." (PMID 35631030, 2022). "More recently, endoglin and syndecan-1 were quantified the mRNA expression and soluble protein levels in dengue cases during febrile, defervescence, and convalescence stages in DF, DFWS, and severe cases compared to non-dengue Other Febrile Illness (OFI) and healthy control." (PMID 35631030, 2022).
dysplasia (3 papers, 2003 to 2013). A usually neoplastic transformation of the cell, associated with altered architectural tissue patterns. "Thus, the patients with refractory cytopenia with multilineage dysplasia (RCMD) showed an abnormal angiogenesis characterised by an increased level of soluble endoglin (sENG)." (PMID 23341958, 2013).
End-Stage Renal Disease (3 papers, 2011 to 2022). "Serum endoglin was measured in 216 patients including 118 with stage 3 or higher CKD and 9 individuals with end stage renal disease (ESRD)." (PMID 21886815, 2011).
invasive breast carcinoma (3 papers, 2009 to 2024). A carcinoma that infiltrates the breast parenchyma. "However, the significance of ENG expression, DNA methylation, immuno-response, and cordycepin (CD) regulation as diagnostic, prognostic, and therapeutic markers for breast invasive carcinoma (BRCA) remains unclear." (PMID 39247590, 2024). "Endoglin has been reported to be highly expressed in the vasculature of various tumour types, including invasive breast carcinomas, and predicts poor survival and poor clinical response to chemotherapy." (PMID 19623180, 2009).
Peritoneal Fibrosis (3 papers, 2022 to 2024). Disorder characterized by a wide range of structural changes in PERITONEUM, resulting from fibrogenic or inflammatory processes. "Knockdown of endoglin by tail vein injection of AAV9-ENG, an adeno-associated virus used for gene therapy, meliorated peritoneal thickening and collagen deposition in a mouse model for peritoneal fibrosis." (PMID 36614087, 2022).
porto-pulmonary hypertension (3 papers, 2016 to 2021). "This is the first mutational analysis of the ENG gene in PAH patients associated to connective tissue disease, human immunodeficiency virus and porto-pulmonary hypertension." (PMID 27260700, 2016).
Pulmonary arteriovenous malformation (3 papers, 2009 to 2023). Pulmonary arteriovenous malformation, a condition most commonly associated with hereditary hemorrhagic telangiectasia, is an abnormal communication between the pulmonary artery and pulmonary vein without an intervening capillary communication. "The phenotypic expression of the disease depends on the mutated gene: for instance, patients with ENG mutations (“HHT1 phenotype”) are more likely to have pulmonary arteriovenous malformations (PAVMs) than patients with ACVRL1 mutations (“HHT2 phenotype”)." (PMID 24603803, 2014). "The genotype-phenotype correlation was consistent with a higher frequency of pulmonary arteriovenous malformations in patients with ENG mutations than in patients with ACVRL1 mutations in our collective." (PMID 19508727, 2009). "The first locus (HHT type 1) was mapped to chromosome 9q33-34, where the 40 kb endoglin (ENG, OMIM 187300) was defined as the affected gene, also associated with a high prevalence of pulmonary arteriovenous malformations." (PMID 19508727, 2009).
pulmonary fibrosis (3 papers, 2010 to 2015). Chronic progressive interstitial lung disorder characterized by the replacement of the lung tissue by connective tissue, leading to progressive dyspnea, respiratory failure, or right heart failure. "Furthermore, several genes that were significantly co-expressed with PEAR1 have also been previously implicated in endothelial-related pathological conditions including pulmonary fibrosis (CTGF) and hemorrhagic telangiectasia (ACVRL1 and ENG)." (PMID 26406321, 2015).
Sepsis (3 papers, 2022 to 2024). Sepsis is defined as life-threatening organ dysfunction caused by a dysregulated host response to infection. "Syndecan-1 and endoglin are crucial components of the glycocalyx, the protective layer lining the luminal surface of ECs; their degradation contributes to microcirculatory dysfunction in sepsis." (PMID 38921594, 2024). "However, further studies are necessary to confirm these results and to clarify the role of endoglin in the pathophysiology of sepsis." (PMID 36117974, 2022). "Although not yet determined in sepsis, circulating levels of soluble endoglin have been shown to be higher in the serum of patients with cardiovascular diseases with a significant inflammatory component." (PMID 36119052, 2022). "Interestingly, in our model we also have identified other novel markers, such as endoglin and PCSK9, whose pathophysiological role in sepsis deserves further investigation." (PMID 36119052, 2022).
bladder cancer (2 papers, 2022 to 2023). "The association of circulating levels of endoglin with bladder cancer remains, however, uninvestigated." (PMID 34587660, 2022). "Urothelium endoglin antibodies have been shown to recognize small‐caliber vessels that are associated with angiogenesis in bladder cancer that can help identify high‐risk patients who could benefit from antiangiogenic therapeutic regimens." (PMID 34587660, 2022).
brain edema (2 papers, 2021 to 2022). Increased intracellular or extracellular fluid in brain tissue. "High levels of soluble ENG are reported in pre-eclampsia, which may be associated with cerebral edema and hemorrhage, which are, in turn, also seen in cerebral I/R-injury." (PMID 35806090, 2022).
capillary malformation (2 papers, 2021 to 2025). "If only ENG and ACVRL1 genes are investigated diagnosis of HHT or capillary malformation-arteriovenous malformation syndrome (HHT-like syndrome) may be delayed or they may remain undiagnosed." (PMID 33807613, 2021).